EGFR (epidermal growth factor receptor)
Diseases named in the same sentence as EGFR in open-access papers (continued):
Sharing a sentence is not in itself a finding about the gene and the disease.
cancer (continued). "Loss of expression of the IGFBPs, IGFBP3 and IGFBP4, has previously been linked with resistance to gefitinib in other cancer types and IGFBP-3 is frequently concomitantly overexpressed with EGFR in ESCC." (PMID 40615716, 2025). "Recently, the importance of CDK1 inhibition in cancer therapy was the subject of a review, and overexpression of EGFR is common in LC." (PMID 39995112, 2025). "EGFr (epidermal growth factor receptor) is a cell surface receptor that plays a vital role in cell signaling and is frequently overexpressed in cancer cells." (PMID 41203700, 2025). "The downregulation of EGFR is also noteworthy, as it is a major driver of proliferation in many cancers." (PMID 40592982, 2025). "In general, our study found that cancer patients with higher Hub-EGFR.Sig risk scores presented poorer DSS and PFI in pan-cancer." (PMID 40574864, 2025). "When EGFR is stabilized by mGluR1, it enhances the migration of cancer cells, thereby accelerating the spread of cancer in brain tissue." (PMID 41154659, 2025). "The mutant EGFR is believed to become constitutively active and transduce proliferative and survival signals, conferring growth advantage upon cancer cells." (PMID 40940888, 2025). "Epidermal growth factor (EGF) receptor (EGFR) is a transmembrane protein overexpressed in various cancers such as lung cancer, breast cancer, head and neck squamous cell carcinoma." (PMID 41140511, 2025). "One of the most extensively studied targets is the EGFR, which is overexpressed in a variety of cancers, including non-small cell lung cancer (NSCLC) and glioblastomas." (PMID 40887613, 2025). "We evaluated also EGFR expression on the MVs surface, as EGFR is a common cancer biomarker previously detected on the cancer cells surface." (PMID 40766966, 2025). "A central focus of targeted cancer therapy is EGFR, an ErbB family receptor tyrosine kinase widely recognized for its clinical relevance." (PMID 41155588, 2025). "Compared to other well-established cancer targets such as B7-H3 42, 43, EGFR 44-46 and MUC-1 47, S15 has rarely been exploited as an immune cell therapy target." (PMID 40365291, 2025). "Many cancer patients receive targeted therapies against upstream regulators of Rsk2, such as EGFR, BRAF, or MEK inhibitors." (PMID 40634321, 2025). "Despite their high risk for BMs, EGFR- and ALK-mutated cancers collectively represent only 17% of the NSCLC population." (PMID 40149325, 2025). "Since EGFR activation represents a major mechanism through which cancer cells evade apoptosis, our data indicate that DHC’s ability to block EGFR phosphorylation contributes critically to its chemosensitizing effects." (PMID 40507823, 2025). "These pathways are consistent with Erlotinib’s known mechanism of action as an EGFR inhibitor, influencing cancer proliferation, senescence, and stress-response pathways, which likely contribute to Erlotinib sensitivity." (PMID 40746727, 2025). "Like many OVs, Ad5NULL-A20 can broaden its therapeutic potential through the design of BICA targeting alternative TAA such as EPCAM and HER2, for applications in cancers that lack EGFR or MICA." (PMID 40741595, 2025). "The EGFR is a multifunctional glycoprotein that is prominently expressed in both normal tissues and various cancer-affected organs." (PMID 40076971, 2025). "Extensive oncological research has characterized EGFR’s fundamental role in cancer cell survival mechanisms." (PMID 40076795, 2025). "The paracrine loops comprising cancerous and stromal cells enable EGFR to facilitate cancer growth and metastasis." (PMID 39942770, 2025). "This treatment method involves the use of drugs that target specific sites within cancer cells, such as EGFR-TKI, thereby inhibiting their growth with precision." (PMID 39744567, 2025). "Identification of the epidermal growth factor receptor (EGFR) in biological specimens is essential for cancer diagnostics, drug development and therapeutic monitoring." (PMID 40368641, 2025).
cancer (continued). "This translocation of EGFR from cancer cells to liver cells can inhibit the action of miRNA-26a/b, activate hepatocyte growth factor (HGF), and promote liver metastasis of cancer cells." (PMID 40309240, 2025). "The MAN2A1-FER fusion facilitates the transport of the FER kinase to the Golgi apparatus, where it activates and promotes cancer through the epidermal growth factor receptor (EGFR) signaling pathway." (PMID 39963268, 2025). "A study conducted on cancer cells has shown that bufalin reduces EGFR protein and expression levels, and the downregulation of AKT and ERK and phosphorylation levels is carried out via bufalin stimulation." (PMID 40172364, 2025). "In particular, EGFR is overexpressed in several types of cancer, including non-small cell lung, bladder, gastric, kidney, ovarian, colorectal, breast, pancreatic cancers and squamous-cell carcinoma of head and neck cancers." (PMID 39940134, 2025). "We then visualized and quantified the oligomerization of the cancer therapeutic target EGFR in the resting state and upon binding to its ligand, EGF, in whole intact cells." (PMID 40328783, 2025). "Here, overlaps between HDV-replication and HDAg-expression can only be found for endocrine resistance and EGFR-inhibition resistance, herpes virus infections and certain types of cancers." (PMID 40537790, 2025). "Two typical anti-cancer drugs targeting EGFR show efficacy against cancer cells by inhibiting EGFR signaling." (PMID 41140511, 2025). "Knockdown of DDOST or treatment with NGI-1 hindered the N-glycosylation of EGFR, obstructing the mechanism by which cancer cells compensate for ERK1/2 activity via EGFR, ultimately leading to lenvatinib resistance." (PMID 41413687, 2025). "LUAD exhibited a particularly high number of 7 mutated genes with significant co-occurrence with CNAs compared to other cancer types – including EGFR, GATA2, GBA, GLI3, KAT6A, KRAS and NOTCH3." (PMID 41415395, 2025). "The proposed cytotoxic mechanism underlying these α-blockers differed in the various cancers and included VEGF, EGFR/HER2, integrin, TNFα, and other mitochondrial apoptotic-inducing factors." (PMID 41154665, 2025). "Metabolic reprogramming, which is a hallmark of cancer, contributes to acquired resistance, and the combination of an EGFR-TKI plus an inhibitor of OXPHOS reverses EGFR-TKI resistance." (PMID 40463905, 2025). "This protein stabilizes the EGFR signaling pathway via its interaction with the cytochrome P450 complex, thereby promoting cancer cell proliferation and enhancing their anti-apoptotic capabilities." (PMID 40098612, 2025). "Agrin expression confers substrate stiffness‐dependent oncogenic attributes to EGFR‐reliant cancer cells." (PMID 40165020, 2025). "Their work demonstrated that Sophoraflavanone G inhibited cancer cell growth and metastasis by downregulating EGFR expression, which in turn suppressed the PI3K/Akt pathway." (PMID 40798865, 2025). "In response to these limitations, researchers developed innovative EGFR/HER-2 dual inhibitors that fight cancers, have fewer side effects, and have enhanced water solubility." (PMID 41036428, 2025). "Further clinical studies are necessary to validate these findings and optimize the use of Lingzhi and Yunzhi in combination with EGFR-TKIs for improved cancer treatment outcomes." (PMID 40733125, 2025). "Previous studies have shown upregulated EGFR expression, especially in cancer cells, as a result of activated signaling pathways." (PMID 40537468, 2025). "EGFR is overexpressed in various cancers, such as non-small cell lung cancer, pancreatic cancer, and colorectal cancer, which is currently one of the most common cancer-driver genes." (PMID 40297810, 2025). "Cetuximab, a monoclonal antibody that inhibits EGFR, is approved for cancer treatment and marketed as Erbitux." (PMID 41516067, 2025).
cancer (continued). "Subsequently, we conducted a comprehensive analysis of 34 pan-cancer scRNA-Seq and 10 bulk RNA-Seq cohorts to identify a representative EGFR-related gene signature (EGFR.Sig)." (PMID 40574864, 2025). "ER stress signaling also facilitates the survival of cancer cells tolerant to EGFR tyrosine kinase inhibitors, and mediates radioresistance subsequent to EGFR inhibition by cetuximab." (PMID 40830980, 2025). "This plethora of anticancer activities, together with the fact that these receptors are found in many different epithelial cancers, made anti‐EGFR agents attractive candidates for the development of molecular drugs in cancer treatment." (PMID 39470386, 2025). "By targeting multiple pathways simultaneously, we can potentially overcome resistance and improve the overall efficacy of EGFR-targeted therapies in cancer treatment." (PMID 40560045, 2025). "Stat3, Akt and ERK1/2 are signaling molecules in the downstream three main signal pathways of the EGFR, which is abnormally activated in various cancer cells." (PMID 40076615, 2025). "Through their multi-domain architecture, tensins integrate mechanical cues from focal adhesions with biochemical signals from receptors (e.g., EGFR, integrins), thereby modulating pathway activities whose dysregulation underpins cancer hallmarks." (PMID 40906372, 2025). "From a biological standpoint, the epidermal growth factor receptor (EGFR) plays a pivotal role in regulating cell growth, migration, stromal invasion, and angiogenesis in many cancers, including CRC." (PMID 41214390, 2025). "Future research must explore uncharted domains to advance our understanding and application of anti-EGFR monoclonal antibodies in cancer therapy." (PMID 41049433, 2025). "This evidence aligns with the efficacy of anti-EGFR treatments in clinical cancer therapies and underscores the need for deeper insight into EGFR-signaling pathways in OS as well as in other cancers." (PMID 39796763, 2025). "In cancer cells, α7-nAChR can formheteromeric complexes with another prooncogenic receptor: the epidermal growthfactor receptor (EGFR)." (PMID 40264586, 2025). "Nowadays, gefitinib has been reported to be used to treat certain types of cancer with high expression of EGFR, including cervical cancer." (PMID 39926646, 2025). "Over the past decade, cancer treatment has progressively shifted towards targeted therapy, with EGFR TKIs emerging as highly effective options for NSCLC patients harboring EGFR mutations." (PMID 40076971, 2025). "For example, several thiadiazole derivatives exhibit potent inhibition of receptor tyrosine kinases like EGFR, which is crucial in many aggressive cancers." (PMID 40906750, 2025). "CAFs contribute to cancer cell resistance against EGFR‐TKIs through various processes, including ECM remodelling, the secretion of soluble molecules, exosomal vesicle delivery and metabolic interactions." (PMID 40162549, 2025). "Despite the availability of targeted therapies for EGFR, hCA_IX and hCA_XII, their single-target focus often limits therapeutic efficacy, as cancer cells can activate compensatory mechanisms to evade treatment." (PMID 40906750, 2025). "By lowering EGFR phosphorylation and raising EGFR degradation, curcumin causes apoptosis in TKI-resistant NSCLC cells, hence preventing the formation of cancer." (PMID 40728967, 2025). "Enrichment analyses (KEGG and Reactome) revealed that differentially expressed genes were enriched in cancer-related pathways, including Wnt/β-catenin signaling, angiogenesis, focal adhesion, and EGFR signaling." (PMID 40941029, 2025). "Epidermal Growth Factor Receptor (EGFR) is a type of membrane RTK that is overexpressed in many cancers." (PMID 40395767, 2025). "Future studies should test novel anti-EGFR therapies in KRASWT cancers, further selected with a complete molecular profile." (PMID 40507311, 2025).
cancer (continued). "Cytotoxic agents targeting the epidermal growth factor receptor (EGFR) exhibit significant potential for cancer therapy as EGFR is overexpressed in various cancers." (PMID 41140511, 2025). "Clinically approved anti-EGFR mAbs have been broadly employed as a treatment for several types of cancer." (PMID 39940647, 2025). "Together, our results identify PRMT1, within the family of type I PRMTs, as the critical isoform to target for reducing cancer persistence in EGFR- or KRASG12C-targeted therapies." (PMID 39699269, 2025). "Curcumin can impede the EGFR signaling pathway in cancer cells by directly or indirectly inhibiting the enzymatic activity of the EGFR intracellular domains, inhibiting EGFR phosphorylation and inducing EGFR ubiquitination." (PMID 40535810, 2025). "In EGFR-activated cancers, AKT phosphorylates TSPAN8 (Ser129), enabling its palmitoylation/cholesterol-dependent nuclear translocation with 14-3-3θ/importin-β." (PMID 40977744, 2025). "We showed that 1 μM osimertinib, an FDA-approved anti-cancer drug/EGFR inhibitor, significantly blocked the EGF-stimulated OAT3 activity." (PMID 40733034, 2025). "Drugs targeting EGFR can inhibit the proliferation, invasion, and migration of cancer cells by blocking relevant signaling pathways to treat GC." (PMID 39923010, 2025). "Targeting AREG represents a promising therapeutic strategy for fibrotic diseases and cancer, particularly in contexts where EGFR-TKIs show limited efficacy." (PMID 40725192, 2025). "Cetuximab and panitumumab are two mAbs directed against EGFR which have previously been approved for the treatment of other types of cancer." (PMID 40003864, 2025). "Laboratory studies confirm its effectiveness against various HER2- and EGFR-expressing cancer cells, including those from breast, lung, and gastric origins." (PMID 41537091, 2025). "GE11 exhibited high selectivity and effective internalization in EGFR-overexpressing cancer cell lines." (PMID 40428099, 2025). "While TIEG1 and Y-box binding protein 1 (YB1) directly bind the EGFR promoter to regulate cancer progression, we demonstrate XBP-1s binds the EGFR promoter." (PMID 41191192, 2025). "Further research into the surface delivery mechanisms of the EGFRL858R mutant and the development of drugs targeting this form of EGFR offers a promising direction for creating more effective treatments for L858R-specific cancers." (PMID 40449599, 2025). "Although previous studies have explored imaging or genomic signatures for predicting EGFR expression in other cancers." (PMID 41179692, 2025). "Cetuximab, a chimeric monoclonal antibody, selectively binds to EGFR, inhibiting its activation and subsequent signaling pathways, hence affecting cancer development and progression." (PMID 40840553, 2025). "As expected, non-smokers and those with EGFR mutant cancers had significantly lower nsSNV, hvSNV and neoantigen load compared to smokers and EGFR wildtype cancer, respectively." (PMID 40770517, 2025). "Other cancer genes detected in focal CNV peaks included EGFR (7p11.2 amplification), MDM2 (12q15 amplification), CCND1 (11q13.3 amplification), and MLLT10 (10p12.31 amplification), which were also enriched in TETs." (PMID 41388389, 2025). "Its intravenous administration ensures rapid systemic action, making it a critical component of therapeutic strategies for cancers overexpressing EGFR, particularly metastatic CRC." (PMID 40777125, 2025). "These proteins have previously been linked to EGFR or KRAS mutations and are known as prognostic markers for NSCLC and other cancers." (PMID 40621945, 2025). "This next‐generation EGFR targeting technology will significantly improve the toolbox for targeted cancer therapy." (PMID 40104837, 2025). "Photocatalytic proximity labeling has subsequently been utilized for high-resolution mapping of other receptor protein microenvironments on cancer cell surfaces, including that of EGFR, c-MET, and HER2." (PMID 39857961, 2025).
cancer (continued). "Treatment of NSCLC with EGFR TKIs such as Osimertinib has been effective until cancer cells acquire resistance to the therapy." (PMID 40943615, 2025). "Gefitinib is a targeted cancer drug, specifically an oral, small molecular tyrosine kinase inhibitor of the epidermal growth factor receptor, primarily used in the treatment of NSCLC with activating EGFR mutations." (PMID 40978098, 2025). "Previously, our research group has reported on diverse estrone analogs’ modulatory effects in different cancers dependent on EGFR expression." (PMID 39942711, 2025). "It was then followed by further immobilization of a Pc‐based fluorophore for bioimaging and the QRH peptide for targeting the EGFR overexpressed in cancer cells." (PMID 39717005, 2025). "Despite limitations such as small sample size, variable scan timing, and potential pre-dosing effects, the study represents a meaningful advance toward refining EGFR-targeted immunoPET for personalized cancer assessment." (PMID 41211421, 2025). "Epidermal growth factor receptor (EGFR), a tyrosine kinase receptor, is involved with cell differentiation and proliferation and is frequently overexpressed in cancer tissues." (PMID 40380992, 2025). "Epidermal Growth Factor Receptor (EGFR) plays a critical role in the development of several cancers." (PMID 41174103, 2025). "EGFR overexpression in TNBC is believed to drive cancer progression through multiple mechanisms, including increased cell proliferation, migration, invasion, angiogenesis, and the inhibition of apoptosis." (PMID 41188939, 2025). "A deeper understanding of how this regulatory axis is perturbed in different cancers underscores the potential of EGFR, MYC and RAS as promising targets for the development of effective treatments for cancer patients." (PMID 39858030, 2025). "In cancer, EGFR signaling often leads to excessive cell proliferation and enhances metastatic potential." (PMID 39941813, 2025). "Subsequent studies identified cancer-associated genetic alterations in cfDNA from the plasma of cancer patients, such as KRAS mutations in pancreatic cancer and EGFR mutations in lung cancer." (PMID 40385463, 2025). "Due to their crucial role in cancer progression, EGFR and its related receptors have become attractive targets for anti-cancer therapies." (PMID 40603466, 2025). "Epidermal growth factor receptor (EGFR) expression by certain types of cancers has been shown to induce radioresistance." (PMID 41227364, 2025). "The epidermal growth factor receptor (EGFR) is a well‐established target for treating cancer, as many malignancies overexpress this receptor, which plays an important role in cell growth and proliferation." (PMID 40104837, 2025). "Two types of drugs used clinically to target EGFR for cancer treatment include monoclonal antibodies and EGFR-TKIs." (PMID 40535810, 2025). "The antagonistic role of RHOB and ABCA7 in cancer reveals that there are complex interactions among Hub-EGFR.Sig, which was also confirmed in our subsequent miRNA–mRNA and TF-mRNA interactive network analysis." (PMID 40574864, 2025). "Taken together, the EGFR cross-talk between glycosylation and phosphorylation is likely a pan-cancer phenomenon in different cancer types, which required further investigations to explore its detailed regulatory mechanism." (PMID 40154885, 2025). "Combining analysis of GO and KEGG enrichment found that these genes were mainly related to proteoglycans in cancer, the prolactin signaling pathway, EGFR tyrosine kinase inhibitor resistance, and the Rap1 signaling pathway." (PMID 40427433, 2025). "Active EGFR (both, under stimulating normal conditions and also in active mutants found in cancer) binds to BECN1 and phosphorylates it at tyrosine residues, promoting its homodimerization and inactivation." (PMID 40754831, 2025).